KLF12 (KLF transcription factor 12)
Diseases named in the same sentence as KLF12 in open-access papers (continued):
Sharing a sentence is not in itself a finding about the gene and the disease.
Obesity (2 papers, 2020 to 2022). Accumulation of substantial excess body fat. "Genetic variants of ULK4, CAV2, HTRA1 and KLF12 are all associated with increased risk of stroke and the orthologous genes were upregulated in brain art ECs in obesity." (PMID 36400935, 2022). "We also found three KO strains which might protect from obesity, Pepd-/-, Klf12+/-, and Pacs1+/-." (PMID 32356724, 2020).
pancreatic ductal adenocarcinoma (2 papers, 2023 to 2025). An infiltrating adenocarcinoma that arises from the epithelial cells of the pancreas. "In pancreatic ductal adenocarcinoma (PDAC), the reader IGF2BP2 interacts with LncRNA-PACERR to enhance the stability and expression of krüppel-like factor 12 (KLF12) and c-MYC mRNAs." (PMID 40066451, 2025).
aneurysm (1 paper, 2015). Bulging or ballooning in an area of an artery secondary to arterial wall weakening. "Furthermore, as an anti-inflammatory regulator, KLF12 is down-regulated in patients with aneurysm, and decidualization and embryo implantation are usually considered to involve proinflammatory responses." (PMID 26223982, 2015).
atherosclerosis (1 paper, 2025). A disease characterized by the build-up of fatty material and calcium deposition in the arterial wall resulting in partial or complete occlusion of the arterial lumen. "Subsequent functional annotation identified eight atherosclerosis-relevant candidate genes: transcription factors (KLF12, KLF6, KLF9, and MEF2C), epigenetic regulators (HDAC9), and signaling molecules (YAP1, SOCS6, and CDC25A)." (PMID 41373654, 2025).
autoimmune disease (1 paper, 2025). A disorder resulting from loss of function or tissue destruction of an organ or multiple organs, arising from humoral or cellular immune responses of the individual to their own tissue constituents. "We examined the association of the PRS-RCDII, derived from three non-HLA genetic variants, namely rs2041570 on chromosome 7p14.3 (FAM188B), rs7324708 on chromosome 13q22.1 (KLF12), and rs205047 on chromosome 17p12 (SHISA6), with 27 unique phecodes related to autoimmune diseases." (PMID 40900534, 2025).
dengue (1 paper, 2010). "Among the genes up-regulated in severe dengue patients are transcription factors that belong to the Kruppel-like factor family (KLF9 and KLF12), which have mainly been studied in the context of development." (PMID 20559541, 2010).
emphysema (1 paper, 2021). "There is insufficient data to clarify that KLF12 is related to emphysema in lung." (PMID 34404834, 2021).
Immunodeficiency (1 paper, 2020). Failure of the immune system to protect the body adequately from infection, due to the absence or insufficiency of some component process or substance. "The associated SNPs in KLF12, rs149473200 and rs147344426, are eQTLs of CD3e molecule (CD3E), a protein coding gene which plays an essential role in T-cell development and its defects cause immunodeficiency." (PMID 33225922, 2020).
pancreatic adenocarcinoma (1 paper, 2019). "By performing KEGG-pathway analysis in the TCGA Pancreatic adenocarcinoma data set, we found that the KLF12 level was positively correlated with Wnt-activated gene signatures, suggesting that KLF12 might be involved in Wnt/β-catenin signaling activation." (PMID 30866999, 2019).
Pleural effusion (1 paper, 2025). The presence of an excessive amount of fluid in the pleural cavity. "Analysis of DEGs in Cycling GZMA and GZMA CD4 T cells from pleural effusion of HP and LCP revealed that seven transcription factors (MLLT3, KLF12, FOXP1, NFKB1, ZEB2, TOX, JAZF1) were upregulated in both cycling GZMA CD4 and GZMA CD4 cells in MPE of LCP." (PMID 40959273, 2025).
premature ovarian failure (1 paper, 2023). "In conclusion, our study revealed a new mechanism by which KLF12 regulates GC apoptosis in the ovarian aging process and provided a new possibility for the clinical treatment of premature ovarian failure to identify targets." (PMID 37543362, 2023).
sudden cardiac arrest (1 paper, 2021). Unexpected rapid natural death due to cardiovascular collapse within one hour of initial symptoms. "KLF12 is a significant quantitative trait locus from multiple GWAS (Genome-Wide Association Studies) for a host of non-pregnancy associated outcomes such as cancers, lipids, eye disorders, sudden cardiac arrest, and heart function abnormalities." (PMID 34880903, 2021).
uterine diseases (1 paper, 2015). "KLF12 belongs to the zinc finger-containing transcription factor family, which contains key mediators of endocrine/metabolic processes that play emerging key roles in human reproductive and uterine diseases." (PMID 26223982, 2015).
tumor (43 papers, 2014 to 2025). "Genes associated with cell migration and proliferation, such as Klf12, Rhoj, and Vctn1, were down-regulated in IL-1R2 deficient tumor cells." (PMID 40767963, 2025). "The lncRNA-PACERR, which binds to IGF2BP2, enhances the stability of KLF12 and c-Myc in the cytoplasm of tumor-associated macrophages (TAMs) in an m6A-dependent manner." (PMID 39897038, 2025). "It has been shown mechanistically that lncRNA-PACERR activates the KLF12/p-AKT/c-MYC pathway by sponging miR-671-3p in tumor-associated macrophages (TAMs)." (PMID 37239940, 2023). "Immunohistochemistry was used to detect the association between KLF12 and β-catenin expression in the subcutaneous implanted tumor." (PMID 30866999, 2019). "To determine whether the KLF12 effect is dependent upon the immune system, we next analyzed the contribution of Klf12 deficiency to tumor growth in immunodeficient mice." (PMID 37606530, 2023). "Hence, we sought to determine whether the anti-tumor phenotype associated with miR-382 overexpression could be rescued by KLF12 or HIPK3 overexpression in miR-382-overexpressing cells." (PMID 25344865, 2014). "Exosomal circ_0007334 in CRC cells was found to directly bind to miR-577 and target Krüppel-like Factor 12 (KLF12) to promote angiogenesis and tumour growth." (PMID 38341827, 2024). "In immunocompetent mice, KLF12 knockout inhibited tumor growth and promoted infiltration of CD8+ T cells." (PMID 37606530, 2023). "On the other hand, KLF12 is a target of and negatively regulated by miR-137, a tumor suppressor in PDAC." (PMID 37239940, 2023). "KLF12 was originally discovered as a suppressor of the transcription factor AP‐2α, which is mainly expressed in tissues such as the brain, kidney, liver, and lung Recently, various studies have indicated that KLF12 is involved in tumor progression." (PMID 37606530, 2023). "Our study showed a positive correlation between KLF12 and PD‐L1 expression in clinical patient tumor tissues." (PMID 37606530, 2023). "In colorectal cancer, KLF12 promotes tumor growth by directly activating early growth response protein (EGR1)." (PMID 37606530, 2023). "We observed that Klf12 KO tumors exhibited similar tumor growth as control tumors, while Klf12 KO tumors maintained lower KLF12 and PD‐L1 expression compared with control tumors." (PMID 37606530, 2023). "The expression levels of KLF12 and EGR1 are associated with poor prognosis of the tumor and serve as potential diagnostic markers and therapeutic targets." (PMID 37606530, 2023). "Mice implanted with ZR-75-30 cells in which the KLF12 expression was knockdown by shKLF12#1 exhibited smaller tumor volume and weight than the control mice." (PMID 37156774, 2023). "Here, we showed that KLF12 is positively correlated with PD‐L1 expression in NSCLC patient tumor tissues." (PMID 37606530, 2023). "But few studies about the relationship between KLF12 and lipid metabolism and lipid browning were reported in tumor cells." (PMID 35787628, 2022). "In recent years, it has been shown that KLF12 can promote tumour proliferation and invasion through PI3K/AKT/c-myc axis." (PMID 35526050, 2022). "KLF12 is a member of kruppel-like factor family, and its tumor suppressive and oncogenic functions in human cancers are increasingly appreciated." (PMID 36482325, 2022). "Some studies have reported that KLF12 enhances tumour malignant progression by participating in transcriptional regulation of oncogenes." (PMID 35526050, 2022). "Meanwhile, tumor suppressors, including KLF12, PRKG1, TRPS1, NOTCH1, RORA, were downregulated in the HSPA8high group." (PMID 33926391, 2021). "In the present study, both the expressions of KLF12 in SiHa cells and tumor tissues based on the HPA database were significantly down-regulated compared with those in normal control cells or clinical samples." (PMID 34950609, 2021). "We also observed that tumor suppressors, including KLF12, PRKG1, TRPS1, NOTCH1, and RORA, were downregulated in the HSPA8high group." (PMID 33926391, 2021).
tumor (continued). "Studies have shown that KLF12 protein can participate in abnormal proliferation and metastasis of tumor cells." (PMID 34644678, 2021). "Beside, the Xenograft model result parallel to the in vitro results, KLF12 overexpression stimulated tumor growth and HIPK3 overexpression induced chemoresistance in LS1034." (PMID 29700213, 2019). "LOC100129148's function as an oncogene to facilitate tumor progression was partially attributed to its ability to acting as a ceRNA for miR-539-5p, and subsequent to activating of the KLF12 signaling pathway in NPC." (PMID 28328537, 2017). "In the present study, we identify KLF12 as a novel candidate tumour-suppressor gene involved in detachment-induced cell death." (PMID 26455320, 2016). "For example, KLF family proteins have been shown to have either a tumor-promoting (KLF4, KLF6, KLF9, KLF10, KLF11, and KLF17) or a tumor-suppressing (KLF5, KLF12) role by intervening in cell signaling associated with proliferation and/or suppression." (PMID 26320172, 2015). "Conversely, knockdown of KLF-12 inhibited tumor growth in a miR-382-knockdown MNNG/HOS xenograft model." (PMID 25344865, 2014). "Many studies have suggested that KLF12 may contribute to tumor development in many types of carcinoma, and that its expression level is closely associated with the progression of malignancy and prognosis." (PMID 37156774, 2023). "Additionally, a positive correlation between KLF12 and PD‐L1 was observed in clinical patient tumor tissues." (PMID 37606530, 2023). "Furthermore, KLF12 has been reported to be a tumor suppressor or inducer tightly dependent on the different signaling crosstalks or partners in a specific cellular environment." (PMID 37156774, 2023). "In ovarian cancer, KLF12 inhibited anoikis resistance and functioned as a tumor suppressor." (PMID 35787628, 2022). "Furthermore, after CD163 + TAMs were sorted from tumour tissues from subcutaneous mice, we observed that the expression of KLF12 and c-myc was significantly decreased in the LncRNA-PACERR knockdown group." (PMID 35526050, 2022). "It has been reported that KLF12 promotes malignant tumour progression via the AKT/c-myc pathway." (PMID 35526050, 2022). "To further validate that KLF12 is participated in the pro-tumour effects of LncRNA-PACERR in TAMs, we got similar results to LncRNA-PACERR by using qPCR, flow cytometry, CCK8, colony formation and Transwell assays, and found that overexpression of KLF12 can promote the expression of LncRNA-PACERR." (PMID 35526050, 2022). "Krüppel-like factor 12 (KLF12) is a eukaryotic transcription factor that is involved in many biological processes, such as organ development, lipid metabolism, decidualization of endometrial stromal cells, proliferation, invasion, and anoikis of tumor cells." (PMID 34644678, 2021). "For example, KLF12 and NFE2L2 were significantly associated with HPV(+) tumours." (PMID 28139702, 2017). "Moreover, our results also demonstrated miR-539-5p exerted its tumor suppressive role on NPC through targeting KLF12." (PMID 28328537, 2017). "Further studies are needed to determine whether KLF12 enhances tumor cell proliferation and/or survival." (PMID 27442508, 2016). "Our results demonstrate that KLF12 promotes tumor growth in CRC." (PMID 27442508, 2016). "Importantly, overexpression of KLF12 increased tumor growth in a miR-382-overexpressing MNNG/HOS xenograft model." (PMID 25344865, 2014). "To determine whether the anti-tumor effects of miR-382 on these OS cells could be partly explained by its targeting of KLF12 and HIPK3, we first analyzed how KLF12 and HIPK3 overexpression affected in vitro and in vivo cell growth and chemosensitivity." (PMID 25344865, 2014).
tumor (continued). "In addition, it was found that KLF12, as a downstream target of miR-137, could participate in tumor cell glycolysis by activating the Wnt/β-catenin pathway through the miR-137/KLF12 axis." (PMID 39816354, 2024). "However, the role of KLF12 in tumor immunity remains obscure." (PMID 37606530, 2023). "Thus, we supposed KLF12 was a tumor suppressor and related with lipid metabolism in ccRCC." (PMID 35787628, 2022). "Moreover, circ-RNF111/miR-876-3p/KLF12 axis could deteriorate the progression of GC by triggering tumor cell growth, metastasis, and glycolysis and curbing apoptosis." (PMID 34461926, 2021). "However, the role KLF12 plays in tumor angiogenesis remains obscure." (PMID 32958011, 2020). "Indeed, KLF12 promotes tumor growth by directly activating early growth response protein 1 (EGR1)." (PMID 27442508, 2016). "Indeed, EGR1 knockdown attenuated the KLF12-induced growth of tumor cell populations." (PMID 27442508, 2016). "PACERR, by interacting with miR-671-3p, activates the KLF12/p-AKT/c-Myc signaling pathway, increases the number of M2-polarized macrophages, and promotes the proliferation, invasion, and migration of tumor cells." (PMID 39897038, 2025). "This interaction derepresses Kruppel-like factor 12 (KLF12), activating the EMT, upregulating MMPs and ATP-binding cassette (ABC) transporters, and ultimately enhancing tumor cell invasion and metastasis." (PMID 40564894, 2025). "In immunocompetent mice, KLF12 knockout increases the infiltration of CD8+ T cells and ultimately mediates tumor regression." (PMID 37606530, 2023). "COL18A1-AS1/KLF12 positively regulated uncoupling protein 1 (UCP1)–mediated lipid browning, which promotes tumor cell “slimming” and inhibits tumor progression." (PMID 35787628, 2022). "Then through literature search, we found that KLF12 is involved in tumor invasion and apoptosis (PMID: 27278159), and there are little studies of KLF12 in NC." (PMID 33820555, 2021). "Considering that KLF family members have been reported to have various effects on vascular endothelial cells and tumor-associated angiogenesis, we speculated that KLF12 might play a critical role in SCLC angiogenesis and that miR-141 promotes neovascularization via KLF12." (PMID 32958011, 2020). "Then, overexpression of KLF12 and HIPK3 significantly stimulated tumor growth and chemoresistance in miR-382-overexpressing LS1034 cell Xenograft models." (PMID 29700213, 2019). "AP-2α expression is reduced in advanced CRC tumor tissues as compared to matched normal tissues and loss of AP-2α promotes invasion of CRC through down-regulation of E-cadherin and up-regulation of matrix metalloproteinase 9 (MMP9), indicating that KLF12 may be involved in CRC." (PMID 27442508, 2016). "In contrast, knockdown of KLF12 and HIPK3 respectively inhibited tumor growth and enhanced chemosensitivity in a miR-382-knockdown MNNG/HOS cell xenograft model." (PMID 25344865, 2014). "Our work led to the identification of a novel functional pathway controlled by miR-382 and its direct targets, KLF12 and HIPK3, that coordinate tumor growth and chemosensitivity, respectively, in OS." (PMID 25344865, 2014). "The in vivo results parallel the in vitro results and show that KLF12 and HIPK3 overexpression stimulate tumor growth and chemoresistance, respectively." (PMID 25344865, 2014). "Overexpression of KLF12 and HIPK3 significantly stimulated tumor growth and chemoresistance in miR-382-overexpressing MNNG/HOS cell xenograft models, respectively." (PMID 25344865, 2014). "Meanwhile the KLF12-transcribed LncRNA-PACERR interacts directly with KLF12 and the KLF12/PACERR complex activates LncRNA-PACERR transcription by recruiting EP300, thereby promoting M2 polarization and pro-tumour function in TAMs." (PMID 35526050, 2022). "The tumor-suppressive miRNAs miR- 451 and miR-539-5p inhibit NPC initiation by targeting the macrophage migration inhibitory factor (MIF) and Kruppel-like factor 12 (KLF12) genes, respectively." (PMID 31456943, 2019).
tumor (continued). "Tumor tissue samples from patients with unfavorable PFS status were found to overexpress four out of the five genes (AGR2, ALDH6A1, TFF2, MCM5) and underexpress KLF12." (PMID 24555920, 2014). "KLF12 is a member of the Krüppel-like factor (KLF) family, whose members function as transcriptional regulators in a multitude of cancer-relevant processes, including tumor cell proliferation, apoptosis, distant metastasis, tumor inflammation and angiogenesis." (PMID 32958011, 2020). "Moreover, luciferase analysis demonstrated that KLF12 was directly regulated by miR-141, and overexpression of KLF12 in miR-141 mimic-transfected HUVECs abrogated the proangiogenic effect of miR-141, thereby confirming that miR-141 promotes SCLC tumor angiogenesis by targeting KLF12." (PMID 32958011, 2020).